ACHE (acetylcholinesterase (Yt blood group))
Diseases named in the same sentence as ACHE in open-access papers (continued):
Sharing a sentence is not in itself a finding about the gene and the disease.
neurodegenerative disease (continued). "The use of nanoencapsulated formulations demonstrated not only the stability of the essential oil but also its increased efficiency in inhibiting AChE, highlighting its therapeutic potential in neurodegenerative diseases." (PMID 40286153, 2025). "These structural features make AChE an attractive target for pharmacological drug design, particularly in the development of inhibitors for the treatment of neurodegenerative diseases." (PMID 40332446, 2025). "Advances are aimed at finding new, highly selective, reversible, and effective inhibitors of AChE to improve treatments for neurodegenerative diseases." (PMID 40332446, 2025). "The extract demonstrated a fourfold stronger AChE inhibition compared to donepezil, suggesting its potential for the treatment of neurodegenerative diseases." (PMID 40697706, 2025). "ASA, abundant in flavonoids, polyphenols, and other anti-oxidative compounds, shows promising potential for treating neurodegenerative diseases by suppressing inflammation, oxidative stress and acetylcholinesterase (AchE) activity." (PMID 38323080, 2024). "Flavonoids have shown potential as natural AChE inhibitors in preliminary in vitro and in silico studies, suggesting their promise as complementary agents for neurodegenerative diseases, particularly AD." (PMID 39796512, 2024). "In neurodegenerative diseases such as AD, elevated AChE levels exacerbate cholinergic dysfunction, leading to impaired cognitive function." (PMID 39598743, 2024). "The complex interplay between AChE, ROS, and neurotoxicity holds significant implications for developing treatments for neurodegenerative diseases." (PMID 39201673, 2024). "There is a close link between the ability of phenolic compounds to exert their neuroprotective effect through their antioxidant and free radical scavenging action and their ability to inhibit enzymes involved in neurodegenerative diseases, such as AChE." (PMID 38397815, 2024). "Our results also indicate a significant inhibition in AChE activity post-treatment, which has been a reliable approach in the management of neurodegenerative diseases, and this inhibition was correspondingly supported by the in-silico data." (PMID 38399415, 2024). "A study using molecular dynamics simulation and binding energy calculations, using AChE as a target, identified diplorethohydroxycarmalol and phlorofucofuroeckol from brown seaweeds as potential lead compounds for neurodegenerative diseases." (PMID 39771015, 2024). "More research is required to determine the efficacy and safety of this compound as a treatment for neurodegenerative diseases like AD because the precise mechanism and degree of its AChE inhibitory effects in the brain are still elusive." (PMID 38487137, 2024). "The capacity of the juice to scavenge free radicals in vitro, as well as its ability to inhibit enzymes associated with neurodegenerative diseases, including MAO-A, MAO-B, and acetylcholinesterase (AChE), were measured." (PMID 39598444, 2024). "The use of furoquinoline alkaloids as inhibitors of AChE and anti-inflammatory agents in neurodegenerative diseases is particularly interesting." (PMID 37628986, 2023). "The capacity to inhibit enzymes that play a role in the progression of neurodegenerative diseases, such as acetylcholinesterase (AChE), butyrylcholinesterase (BChE), and tyrosinase was also studied." (PMID 37891906, 2023). "The AChE inhibitors play an important role in the treatment of neurodegenerative diseases e.g., Alzheimer’s disease (AD)." (PMID 37298103, 2023). "Collectively, our efforts present compound 3bc as a multifunctional molecule inhibiting MAO-B, AChE, and neuroinflammation for the possible management of neurodegenerative diseases." (PMID 37237899, 2023). "Currently, the treatment of neurodegenerative diseases is based on drugs being either AChE inhibitors or antagonists of N-methyl-D-aspartate (NMDA) receptors." (PMID 37298103, 2023).
neurodegenerative disease (continued). "Numerous marine natural products have been reported with neuroprotective properties in experimental models for neurodegenerative diseases, including acetylcholine esterase (AChE) inhibition." (PMID 37623727, 2023). "The combined axial roles for MAOs and AChE in the theory of multiple mechanisms of neurodegeneration stimulate the development of bifunctional molecules, inhibiting both MAO and AChE activities to combat neurodegenerative diseases." (PMID 37237899, 2023). "Another protein that has appealed to researchers investigating the role of N-glycans in neurodegenerative diseases is the enzyme responsible for the degradation of the neurotransmitter acetylcholine, acetylcholinesterase (AChE)." (PMID 36408389, 2022). "Several plants and phytochemical compounds exhibit antioxidant, anti-inflammatory and AChE inhibitory capacities and therefore, can be valuable in the management of neurodegenerative diseases especially cognitive disturbances related to these diseases." (PMID 35782773, 2022). "Another pathological symptom of neurodegenerative diseases is a decreasing level of the protein LRP1 or of AChE itself." (PMID 35739872, 2022). "According to Sharma, the declining level of AChE in neurodegenerative diseases leads to the accumulation of large amounts of acetylcholine and to overstimulation of the cholinergic system." (PMID 35739872, 2022). "In neurodegenerative diseases, the activities of AChE and BuChE are high, leading to cholinergic deficits." (PMID 35458597, 2022). "The biosensor developed showed sufficient sensitivity toward donepezil and berberine, drugs used in the therapy of neurodegenerative diseases, and carbofuran as a representative of irreversible AChE inhibitors." (PMID 36140061, 2022). "LPS is known to increase pro-inflammatory cytokines and AChE activity, which leads to neurodegenerative diseases." (PMID 33046678, 2021). "The aim of this review is to present the role of AChE in the pathogenesis of neurodegenerative diseases." (PMID 34502198, 2021). "The aim of this review is to present the role of AChE in the pathomechanism of neurodegenerative diseases." (PMID 34502198, 2021). "In the perspective of discovering new multitarget agents for AD, we selected some candidates for their evaluation as inhibitors of AChE and MAOs, two target enzymes involved in neurodegenerative diseases." (PMID 33297547, 2020). "Currently, natural products constitute one of the main sources of the AChE inhibitors, used as active compounds to treat damages to central and peripheral nervous system, as well as to alleviate symptoms of neurodegenerative diseases." (PMID 32991579, 2020). "The enzymes acetylcholinesterase (AChE) and butyrylcholinesterase (BChE) are primary targets in attenuating the symptoms of neurodegenerative diseases." (PMID 31899981, 2020). "It is a famous AChE inhibitor and has been used in treating neurodegenerative diseases, including AD." (PMID 32210182, 2020). "AD is a complex neurodegenerative disease leading to impaired cognition, and drugs targeting AChE represent the primary treatment method in the modern clinic." (PMID 33327436, 2020). "Study reported that 1,8 cineole inhibits AChE in vitro, improves cognition and reported to have an anti-inflammatory action in neurodegenerative disease like AD." (PMID 31114535, 2019). "Previous findings have shown that SCOP can induce an elevation in rats’ AChE activity, thereby mimicking the pathophysiology of many neurodegenerative diseases." (PMID 29983948, 2018). "Present findings are interesting given the presence of oxidative stress, as well as the implication of AChE in the early stages of neurodegenerative diseases." (PMID 28411556, 2017). "Future studies would do well to assess the chronic effect of oxidative stress on AChE in animal models of neurodegenerative diseases." (PMID 28411556, 2017).
neurodegenerative disease (continued). "AD is a complex neurodegenerative disease involving multiple targets such as AChE, BuChE, BACE 1, MAO A and NMDA." (PMID 29078760, 2017). "As some neurodegenerative diseases have been related with changes in AChE activity along with an increase in oxidative stress, we measured the AChE activity from SH-SY5Y cells which were used as enzyme source." (PMID 28411556, 2017). "Among the four known proteins interacting with icariin, two proteins (PDE5 and AchE), were included in 798 neurodegenerative disease-related proteins on account of the availability of PDB structures." (PMID 26784184, 2016). "Further studies will be required for exploring the biological significance of this finding, for example under stress conditions or in neurodegenerative disease, where ACHE gene expression is altered." (PMID 18545673, 2008). "In researchon neurodegenerative diseases such as Alzheimer’s, derivativeshave been developed with multitarget activities, including the inhibitionof cholinesterases (AChE/BuChE), secretases (BACE1), and modulationof γ-secretase, in addition to showing anti-inflammatory potentialby inhibiting COX-2." (PMID 41585699, 2026). "This suggests that it may be reasonable to revisit the other inhibitors of AChE as well, and validate their mechanism of action, especially taking into account the important role of those compounds in the therapies for neurodegenerative diseases." (PMID 39860281, 2025). "As molecular docking and MD simulations continue to evolve, their combined application will remain a cornerstone in the development of highly selective, reversible, and effective AChE inhibitors, paving the way for improved therapeutic strategies against neurodegenerative diseases." (PMID 40332446, 2025). "Beyond enriching the chemical knowledgebase of an under-investigated sponge, this integrated approach mayaccelerate the discovery of novel AChE agents, with potential relevancefor neurodegenerative disease research." (PMID 41179172, 2025). "The potent inhibitory activity of AChE and BChE indicates the potential use of these derivatives in the treatment of neurodegenerative diseases, while the ability to inhibit α-glucosidase suggests potential use in the treatment of type 2 diabetes by reducing carbohydrate absorption." (PMID 40286078, 2025). "Several compounds, including ellagic acid, quercetin, curcumin, kaempferol, and hesperetin, display relatively high binding affinities for both AChE and Amyloid-β, suggesting their potential as dual-targeting agents for the treatment of neurodegenerative diseases like Alzheimer’s." (PMID 39850118, 2025). "These compounds act by inhibiting AChE and BuChE that may contribute to the management of neurodegenerative diseases." (PMID 41295407, 2025). "These compounds displayed both AChE inhibitory and antioxidant activities, highlighting their dual role in enhancing cholinergic transmission and reducing oxidative stress, two central mechanisms in neurodegenerative disease progression." (PMID 41295407, 2025). "Systematic exploration of the metabolic pathways in related species could yield novel AChE inhibitors or other metabolites targeting neurodegenerative diseases." (PMID 39974736, 2025). "Overall, these studies provide evidence of the potential of this new class of photoswitchable compounds, able to synergistically inhibit the two neurodegenerative disease‐related enzymes AChE and MAO‐B, with the added value given by the possibility of photomodulating their pharmacological effect." (PMID 40123150, 2025). "Additionally, the extract was found to be a highly active inhibitor of acetylcholinesterase (AChE), potentially suggesting the applicability of this extract in the prevention of neurodegenerative diseases, including Alzheimer’s disease." (PMID 38067623, 2023).
neurodegenerative disease (continued). "For example, compounds with ability to inhibit acetylcholinesterase (AChE) are promising molecules to develop new drug leads for neurodegenerative diseases treatment, such as Alzheimer’s and Parkinson’s diseases, as these pathologies are characterized by a decrease in acetylcholine release." (PMID 37240175, 2023). "Therefore, this work aimed to identify new candidate molecules inhibiting MAOs and AChE as well as microglia-mediated neuroinflammation for the development of potential agents for the management of neurodegenerative diseases." (PMID 37237899, 2023). "Moreover, the inhibition of all these compounds against AChE, an important neurodegenerative disease target, was also screened, whereas they were all inactive." (PMID 36613392, 2023). "Moreover, AChE inhibitors are currently utilized for AD patients, and the discovery of AChE inhibitors is still a hot topic in the treatment of AD and other neurodegenerative diseases." (PMID 35897815, 2022). "Therefore, AChE and BChE inhibitors are now widely used in the treatment and prevention of neurodegenerative diseases." (PMID 35458770, 2022). "The present finding suggests that the tea infusions possess bioactive compounds that could decrease neurodegeneration or treat neurodegenerative diseases by modulating the activity of AChE." (PMID 36199544, 2022). "Acetylcholinesterase (AChE) is involved in inflammatory reactions, neuronal apoptosis, oxidative stress and the aggregation of pathological proteins, which are closely related to the pathogenesis of neurodegenerative diseases." (PMID 35646138, 2022). "The design and search for new drugs targeting AChE may in the future allow for the discovery of a therapies that will be effective in more neurodegenerative diseases, due to the fact that this enzyme plays a significant role in most of them." (PMID 34502198, 2021). "AChE is an enzyme that is responsible for the degradation of acetylcholine (ACh), and its inhibition results in increased acetylcholine levels, thus improving the cognitive symptoms of neurodegenerative diseases." (PMID 33466604, 2021). "Designing and searching for new drugs targeting AChE may in the future allow the discovery of therapies that will be effective in the treatment of neurodegenerative diseases." (PMID 34502198, 2021). "AChE plays an important role in the neurodegenerative diseases." (PMID 34502198, 2021). "AChE has a pivotal role in memory and learning, therefore increased knowledge on AChE function may facilitate the development of further, more effective therapies towards neurodegenerative diseases, like AD." (PMID 32155996, 2020). "Acetylcholinesterase (AChE) inhibitors such as donepezil, galanthamine, rivastigmine, and tacrine are the most prescribed medications used to slow down the progression of cognitive decline in neurodegenerative diseases." (PMID 32586060, 2020). "Therefore, AChE is considered as an important therapeutic target, and numerous reversible inhibitors of AChE are being clinically used as a memory enhancer in epileptic patients and other neurodegenerative diseases." (PMID 32235506, 2020). "Due to their antioxidant activity and AChE inhibition, these novel compounds may be considered as leads for investigations in neurodegenerative diseases." (PMID 32249705, 2020). "Many reports have demonstrated that AChE inhibitors from plant materials could be potentially used as therapeutic agents for neurodegenerative diseases like AD." (PMID 31057649, 2019). "The methodology followed here have highlighted many molecules with a higher affinity towards AChE and these findings may take lead molecules generated in preclinical studies to treat neurodegenerative diseases." (PMID 31150404, 2019). "The identification of these AChE-inducing natural products could be very useful in finding potential drugs or food supplements for possible new therapeutic opportunities in neurodegenerative diseases." (PMID 29535608, 2018).
neurodegenerative disease (continued). "Thus, injuries of these neurons are related to reductions in ACh levels and excessively increased AChE activity in neurodegenerative diseases, such as AD, and contribute to learning and memory dysfunction." (PMID 29670659, 2018). "The cholinesterase inhibitory activity was 7.38 ± 0.03 and 5.74 ± 0.06 mmol GALAE/kg, for the inhibition of acetylcholinesterase AChE and BChE, respectively, showing that this plant is a candidate for the isolation of compounds that can be useful for the treatment of neurodegenerative diseases." (PMID 29734888, 2018). "In view of these brain beneficial functions, genistein could be a good candidate for treatment of neurodegenerative diseases via regulation of AChE." (PMID 29535608, 2018). "Our results are in concordance with the previous recent reports that any substance which have AChE inhibitory and antioxidant activities could be considered as an ideal and potent agent for management of neurodegenerative diseases." (PMID 29875670, 2018). "Furthermore, AChE would induce neuronal apoptotic and berberine-mediated inhibition of AChE has broadly effect on a great number of neurodegenerative diseases." (PMID 27769241, 2016). "They found enhanced AChE activity with these inflammatory markers after LPS administration indicates a possible relationship between neuroinflammation and cholinergic system during the development of neurodegenerative diseases." (PMID 25374508, 2014). "However, many of the prominent features of developmental processes are recapitulated in degenerative disease and are similarly accompanied by changes in AChE and α7-nAChR expression." (PMID 19287501, 2009). "Hence, an important role in the therapy for this neurodegenerative disease is played by the drugs from the group of acetylcholinesterase (AChE) inhibitors, which inhibit the development of degenerative changes for a certain period of time, although they do not eliminate its causes." (PMID 39860281, 2025). "Therefore, efficient treatments for neurodegenerative diseases may involve the discovery of effective AChE activity inhibitors." (PMID 40284441, 2025). "Additionally, molecular docking studies with human phosphodiesterase 4B, AChE, and BuChE also support the proposal that the top candidate compounds could benefit future neurodegenerative disease treatment." (PMID 37894669, 2023). "The demonstrated significant activity towards the inhibition of COX and AChE under the proposed conditions suggests that future research on cellular or animal models would be useful to confirm the effectiveness of cranberry extracts in inhibiting some diseases, especially neurodegenerative diseases." (PMID 38067623, 2023). "Currently, AChE inhibitors are one of the major classes of approved drugs to treat AD; therefore, many research studies are still being devoted to the identification of novel agents with AChE inhibitory properties for the treatment of this neurodegenerative disease." (PMID 33466604, 2021). "Since the selected extracts have shown inhibitory properties on AChE and present antioxidant activity, these results may provide an initial contribution to the possible development of a nutraceutical-targeting degenerative disease and presenting beneficial effects on health." (PMID 32575531, 2020). "Furthermore, BBR’s inhibitory effects on AChE could lead to effects on a great number of neurodegenerative diseases as AChE has exhibited apoptotic induction, in addition to its general role as antagonist to acetylcholine." (PMID 25749423, 2015). "These pathways were, in general, shared across all neurodegenerative diseases, even though the major overlap was found for the synaptic functions (BDNF, CCL2, ACHE, GFAP, NEFH or NEFL) and microglia pathways (TREM2, IL13, IL6R IFNG)." (PMID 41250190, 2025).